SIRT3 (sirtuin 3)
Diseases named in the same sentence as SIRT3 in open-access papers (continued):
Sharing a sentence is not in itself a finding about the gene and the disease.
cardiac hypertrophy (continued). "The aims of the present study were to examine whether exogenous H2S supplement attenuated isoproterenol- (ISO-) induced myocardial hypertrophy in SIRT3 knockout (KO) mice." (PMID 30647820, 2018). "Associated with the similar effect on blood pressure and H2S concentration in all the mice, SIRT3 might be the critical factor on the protective effects against myocardial hypertrophy by H2S." (PMID 30647820, 2018). "We further investigated whether exogenous H2S supplement improved ISO-induced myocardial hypertrophy in a SIRT3-dependent manner." (PMID 30647820, 2018). "Also, cardiac-specific SIRT3 overexpression prevented angiotensin II- and doxorubicin-induced cardiac hypertrophy, fibrosis, and fetal gene expression confirming that SIRT3 has a role in protecting the heart against hypertrophic stimuli." (PMID 30131726, 2018). "Improved autophagy by Sirt3 activation also ameliorates myocardial hypertrophy." (PMID 30021848, 2018). "The pleiotropic effects of SIRT3 activation in the prevention of mitochondrial ROS could be a crucial pathway to the inhibition of cardiac hypertrophy." (PMID 30131726, 2018). "In addition, RIP140, which is involved in the pathogenesis of cardiac hypertrophy and heart failure, also inhibits SIRT3." (PMID 29643974, 2018). "Our previous work demonstrated that SIRT4 promotes angiotensin II-induced development of cardiac hypertrophy by inhibiting the interaction of SIRT3 and MnSOD, which increases MnSOD acetylation levels, decreases its activity and leads to elevated ROS accumulation." (PMID 30574122, 2018). "In conclusion, SIRT3 has a crucial role in the development and progression of cardiac hypertrophy." (PMID 30131726, 2018). "In response to hypertrophic stimuli, SIRT3 deficient mice developed severe cardiac hypertrophy, in contrast to SIRT3-overexpressing mice that did not respond to these stimuli." (PMID 30131726, 2018). "SIRT3 interacts with FOXO3a to activate antioxidant genes like manganese superoxide dismutase (MnSOD) and catalase, whose gene products reduce ROS while positively affecting disorders like cardiac hypertrophy and interstitial fibrosis." (PMID 27686535, 2017). "Correspondingly, HKL attenuates pathologic cardiac hypertrophy and fibrosis by activating SIRT3." (PMID 28423723, 2017). "SIRT3‐mediated deacetylation activates enzymes responsible for reducing ROS in protective action against oxidative stress‐dependent phenomena or diseases such as cardiac hypertrophy, aging, cancer, cardiac dysfunction, and neural degeneration." (PMID 27686535, 2017). "SIRT3 knockout mice also showed the signs of cardiac hypertrophy." (PMID 28197299, 2017). "Conversely, downregulation or absence of SIRT3 was associated with decreased cardiac recovery and increased infarct size, enhanced doxorubicin-induced cardiac hypertrophy and H2O2-induced neuronal injury." (PMID 28559847, 2017). "Furthermore, lipid accumulation-induced cardiac hypertrophy was mitigated by SIRT3 mediated deacetylation of long chain acyl CoA dehydrogenase (LCAD)." (PMID 28423723, 2017). "Consequently, reduced SIRT3 levels are reported in several models of cardiac hypertrophy and heart failure." (PMID 28423723, 2017). "Altogether, these results indicated that Sirt3 might be involved in preventing myocardial hypertrophy." (PMID 27880725, 2016). "To validate whether Sirt3 during myocardial hypertrophy was protective, we subjected both the WT and Sirt3-KO mice to chronic AngII infusion for four weeks." (PMID 27880725, 2016). "Nevertheless, whether there are other regulatory signalling pathways for Sirt3 to alleviate myocardial hypertrophy remains a mystery." (PMID 27880725, 2016). "Based on the evidence presented in the previous paragraphs, impaired SIRT3 activity may play an important role in the pathogenesis of cardiac hypertrophy, heart failure, and IR injury." (PMID 27790619, 2016). "SIRT3−/− mice spontaneously develop cardiac hypertrophy with increasing age." (PMID 27790619, 2016).
cardiac hypertrophy (continued). "Deacetylation of FoxO1 by Sirt3 promotes autophagy and alleviates myocardial hypertrophy." (PMID 27880725, 2016). "Sirt3 protects cardiomyocytes from oxidative stress and suppresses cardiac hypertrophy." (PMID 27690014, 2016). "SIRT3 has been reported to repress the activation of Akt in cardiac hypertrophy, we therefore hypothesized that SIRT3 could inhibit oncoproteins via the Akt pathway in prostate cancer." (PMID 26317998, 2015). "Sirt3 is known to improve cardiac metabolisms, limit the cardiac fibrosis and cardiac hypertrophy." (PMID 25311234, 2015). "Pillai and colleagues showed that honokiol, a natural occurring compound from the bark of magnolia trees with anti-inflammatory, anti-oxidative, anti-tumor, and neuroprotective properties, reverses murine cardiac hypertrophy and fibrosis by a SIRT3-dependent mechanism." (PMID 26370974, 2015). "Our findings suggested that SIRT3 may block cardiac hypertrophy by inhibiting lipid metabolism disorders and attenuate lipid accumulation in the mitochondria through the deacetylation of LCAD." (PMID 25748450, 2015). "Our findings suggest that SIRT3 may block heart hypertrophy by inhibiting lipid metabolism disorders and attenuate lipid accumulation in the heart mitochondria through the deacetylation of LCAD." (PMID 25748450, 2015). "Knockout of Sirt3 in mice promotes angiotensin II-induced cardiac hypertrophy." (PMID 25192254, 2014). "In contrast, knockout of Sirt3 promoted angiotensin II-induced cardiac hypertrophy in mice." (PMID 24039710, 2013). "Overexpression of Sirt3 blocked cardiac hypertrophy by suppressing ROS formation." (PMID 24039710, 2013). "In addition, it has also been shown that the Sirt3 knockout mice are permissive for other age-related illnesses including fatty liver, insulin resistance, and cardiac hypertrophy." (PMID 21386137, 2011). "Recently, the protective effect of Sirt3 under oxidative stress was shown in cardiomyocytes, where it was shown that Sirt3 reduced ROS generation in cardiomyocyte under cardiac hypertrophy by enhancing antioxidant enzymes such as manganese superoxide dismutase (MnSOD) and catalase." (PMID 21390294, 2011). "Together, these data show for the first time that SIRT3 activity is necessary to prevent mitochondrial dysfunction and cardiac hypertrophy during aging and shed light on new pharmacological approaches to delaying aging and treating diseases in cardiac muscle and possibly other post-mitotic tissues." (PMID 21212461, 2010). "However, SIRT3 can inhibit cardiac hypertrophy by participating in the deacetylation of histone H3." (PMID 40710369, 2025). "Interestingly, It has been suggested that Chronic dietary capsaicin could activate TRPV1 to restore Complex I function then up-regulating Sirt3 expression to reverse cardiac hypertrophy." (PMID 39266965, 2024). "Thus, decreased ATAD3A oligomerization under cardiac hypertrophy may result from decreased SIRT3 activity." (PMID 38250153, 2024). "Together, our results demonstrate that 2-APQC is a targeted SIRT3 activator that alleviates myocardial hypertrophy and fibrosis by regulating mitochondrial homeostasis, which may provide a new clue on exploiting a promising drug candidate for the future HF therapeutics." (PMID 38744811, 2024). "Indeed, it has been demonstrated that the production of ROS is an essential mechanism for the development of cardiac hypertrophy and that SIRT3 is able to control its accumulation, consequently blocking the activation of pathways, such as MAPK/ERK and PI3K/AkT, involved in cardiac hypertrophy." (PMID 37686073, 2023). "It is been demonstrated that activation of AMPK‐PGC‐1α‐SIRT3 signaling pathway could preserve myocardial function by reducing mitochondrial oxidative stress and enhancing mitochondrial biogenesis in the context of cardiac hypertrophy." (PMID 35171536, 2022).
cardiac hypertrophy (continued). "Furthermore, the SIRT3 substrate FOXO3a regulated apoptosis and mitophagy, and SIRT3 activated its activity and nuclear translocation, thereby enhancing antioxidant defense against cardiac hypertrophy." (PMID 36192726, 2022). "Increased mitochondrial SIRT3 activity is associated with reduced acetylation of SIRT3 substrates, MnSOD, and oligomycin-sensitive endogenic protein (OSCP), which reduced ROS synthesis by increasing mitochondrial oxygen consumption rate, thereby preventing cardiac hypertrophy." (PMID 35855865, 2022). "The impact of SIRT in cardiac physiology and pathology has gained an increasing consideration in recent years and proved that impaired SIRT3 activity might play roles in the pathogenesis of various cardiac dysfunctions, such as cardiac hypertrophy, IR injury, and heart failure." (PMID 35224092, 2022). "In this study, we showed that SIRT3 modulated the deacetylation of CypD to control the opening of mPTP in chondrocytes, which was in accordance with other studies showing that SIRT3 mediated the deacetylation of CypD in aging-related cardiac hypertrophy or breast carcinoma." (PMID 34943075, 2021). "SIRT3 prevents cardiac hypertrophy through FoxO3 activation, with subsequent induction of MnSOD, resulting in reduced intracellular ROS concentration, thus suppressing ROS-induced mitogen-activated protein kinases which could otherwise directly promote hypertrophy, such as Ras and Akt/PI3K." (PMID 34899370, 2021). "Similarly, Emodin, as the main component of rhubarb, could effectively block ISO- and TAC-induced cardiac hypertrophy through Sirt3-dependent mitochondrial protection." (PMID 35118147, 2021). "In addition, SIRT3 can regulate a series of substrates to block cardiac hypertrophy." (PMID 32724473, 2020). "Interestingly, SIRT3 reduces cardiac hypertrophy through increasing Foxo3a-dependent antioxidant defense mechanisms, suggesting that SIRT3 is an endogenous negative regulator of cardiac hypertrophy that protects the heart by suppressing cellular levels of ROS in mice." (PMID 32499759, 2020). "Moreover, SIRT3 may also attenuate doxorubicin-induced cardiac hypertrophy and mitochondrial dysfunction via suppression of BNIP3." (PMID 29643974, 2018). "Additionally, whether the SIRT3 signal pathway is involved in the possible protection against myocardial hypertrophy by DMY remains unknown." (PMID 30200365, 2018). "In addition, SIRT3-/- mice developed age- and stress-induced cardiac hypertrophy." (PMID 28559847, 2017). "In addition, the LVPW and HW/BW increased with aging, implying that SIRT3-KO mice could have spontaneous cardiac hypertrophy." (PMID 25748450, 2015). "Cat SIRT3 expression in the heart may be related to protection against cardiac hypertrophy." (PMID 24073959, 2013). "In porcine models of myocardial hypertrophy, UTMD-facilitated Sirt3 gene delivery demonstrates therapeutic efficacy by enhancing sustained cardiac functional recovery while attenuating pathological myocardial remodeling." (PMID 40959490, 2025). "In cardiac hypertrophy, SIRT4 can be detrimental by increasing ROS levels through its interaction with SIRT3 and MnSOD." (PMID 40799515, 2025). "Dihydromyricetin ameliorated myocardial hypertrophy and fibrosis in DCM through activation of SIRT3, inhibition of oxidative stress, inflammation, and apoptosis, demonstrating its medical potential in DCM treatment." (PMID 41276460, 2025). "SIRT1 and SIRT3 protect cardiomyocytes by enhancing the deacetylation of PGC-1α, reducing oxidative stress, and inhibiting the occurrence of cardiac hypertrophy." (PMID 40710369, 2025). "During cardiac hypertrophy, the expression levels of SIRT1, SIRT3, and PGC-1α (peroxisome proliferator-activated receptor γ-coactivator 1α) are significantly reduced." (PMID 40710369, 2025).
cardiac hypertrophy (continued). "We used immunohistochemical testing on mouse heart tissue and found that after SIRT3 knockout, myocardial hypertrophy and fibrosis were aggravated, and treatment with 2-APQC alleviated myocardial hypertrophy and myocardial cell fibrosis." (PMID 38744811, 2024). "In the heart failure mouse model and SIRT3 knockout mouse model, 2-APQC inhibited myocardial hypertrophy and relieved myocardial fibrosis by regulating the AKT-mTOR and TGF-β-Smad3 signaling pathways through SIRT3 activation." (PMID 38744811, 2024). "Recent studies have supported an interaction between SIRT3 and PARP‐1 in chronic disorders, such as cardiac hypertrophy and diabetic retinopathy." (PMID 39215404, 2024). "We previously reported that SIRT3 inhibits cardiac hypertrophy and ISO stimulation resulted in downregulation of SIRT3 expression." (PMID 38250153, 2024). "It has been shown that, by interacting with PARP1, SIRT3 inhibits the acetylation of PARP1, thereby reducing the activity of PARP1 to inhibit cardiac hypertrophy." (PMID 37834477, 2023). "Given that Honokiol is the pharmacological activator of Sirt3,19 and AMPK‐SIRT3 axis has pivotal role in pathophysiological process of cardiac hypertrophy, we analyzed the expression profile of AMPK and SIRT3 in heart lysates of each group." (PMID 35171536, 2022). "The expression of SIRT1, SIRT3, and PGC-1α (Peroxisome proliferator-activated receptor gamma coactivator-1 alpha) were decreased in cardiac hypertrophy." (PMID 35958418, 2022). "It was found that SIRT3 activates SOD2 and catalase to block cardiac hypertrophy in primary cardiomyocytes cultures, thereby decreasing ROS levels." (PMID 35571098, 2022). "For instance, SIRT3 deacetylated ECHS1, which repressed cardiac hypertrophy by inhibiting histone crotonylation." (PMID 35855341, 2022). "SIRT1 and SIRT3 enhance the deacetylation of PGC-1α, reduce oxidative stress and prevents cardiac hypertrophy." (PMID 35958418, 2022). "SIRT3 can modify mitochondrial antioxidant superoxide dismutase 2 (SOD2) to reduce oxidative stress and prevent the development of cardiac hypertrophy." (PMID 36036085, 2022). "SIRT3, which is a mitochondrial NAD+-dependent deacetylase in the sirtuin family, has been shown to correlate with several diseases, such as cardiac hypertrophy, acute kidney injury, and acute lung injury." (PMID 36100663, 2022). "Our results suggested that quercetin protected mitochondrial function by modulating SIRT3/PARP-1 pathway, contributing to the inhibition of cardiac hypertrophy." (PMID 34776960, 2021). "The mitochondrial SIRT3 and SIRT5 were cardiac protective factors that repress aging and pathological cardiac hypertrophy, whereas SIRT4 was reported as the only member as a pro-hypertrophic member." (PMID 33611744, 2021). "In the cardiac hypertrophy model of ISO-stimulated SD rats, the interaction between SIRT3 and PARP-1 was enhanced, whereas the level of acetylation of PARP-1 was also increased." (PMID 32139662, 2020). "The results showed that NAD+ was significantly reduced in the cardiac hypertrophy model of ISO-stimulated SD rats, suggesting that SIRT3 activity was reduced under ISO stimulation." (PMID 32139662, 2020). "Previous studies indicated that SIRT3-mediated deacetylation of FOXO3 decreased cellular ROS levels and ameliorated cardiac hypertrophy in mice." (PMID 33298860, 2020). "Previous studies revealed that Ang II-induced cardiac hypertrophy is mediated by AMPK-, Sirt3-, and PPARγ- dependent mechanisms." (PMID 31636805, 2019). "In other words, although H2S plays diverse roles on MAPK signal pathway with different status, H2S-attenuated myocardial hypertrophy is, in part, mediated through blocking the ERK pathway via a SIRT3-dependent manner." (PMID 30647820, 2018). "In the present study, we explored the role of DMY on myocardial hypertrophy induced by transverse aortic constriction (TAC) and investigated the SIRT3-related signal molecules to elucidate possible mechanisms." (PMID 30200365, 2018).
cardiac hypertrophy (continued). "Previous study suggested that SIRT3 promoted autophagy by forkhead-box-protein 1 (FOXO1) deacetylation, thereby ameliorating Ang II induced myocardial hypertrophy." (PMID 30200365, 2018). "Similar to SIRT3, SIRT6 knockdown mice showed cardiac hypertrophy and the overexpression of SIRT6 rescues cardiac hypertrophy." (PMID 28197299, 2017). "Study on cardiac hypertrophy shows that exogenous NAD+ elevates cellular NAD+ levels and activates SIRT3." (PMID 27240523, 2016). "To date, three family members—SIRT1, SIRT3, and SIRT7—havebeen shown to block stress-induced cardiac hypertrophy by impinging upon ROSgeneration." (PMID 20375467, 2010). "SIRT3 knockout mice are also hypersensitive to heart stress induced by transverse aortic constriction (TAC), as evidenced by cardiac hypertrophy, fibrosis, and increased mortality." (PMID 21212461, 2010). "Although Sirt3 has been shown to improve mitochondrial function by deacetylating mitochondrial proteins, enhancing autophagy, and inhibiting myocardial hypertrophy, the specific molecular mechanisms are still not fully understood." (PMID 40800583, 2025). "This activation influences key signaling pathways, including the mTOR-p70S6K, JNK, and TGF-β/Smad3, effectively reducing ISO-induced myocardial hypertrophy and fibrosis rat heart failure in vitro and in vivo models, and confirmed the targeting of 2-APQC in SIRT3 knockout mice." (PMID 38744811, 2024). "Compared with the ISO group, the ISO + 2-APQC group showed no improvement in symptoms of myocardial hypertrophy and fibrosis after SIRT3 knockout." (PMID 38744811, 2024). "It is noteworthy that in a study of angiotensin II (Ang II)-induced cardiac hypertrophy in mice, it was demonstrated that SIRT4 inhibited the binding of MnSOD to SIRT3, resulting in increased MnSOD acetylation and elevated ROS accumulation upon Ang II stimulation." (PMID 37998340, 2023). "Sirtuin 3 (SIRT3) is a type III histone deacetylase, which can inhibit cardiac hypertrophy." (PMID 37834477, 2023). "Although many studies have described SIRT3 impairment in LPS-induced ALI, cisplatin-induced AKI, cardiac hypertrophy, Alzheimer’s disease, Parkinson’s disease, and cancers, we found that abdominal surgery under sterile inflammation resulted in SIRT3 deficiency in mesothelial cells." (PMID 36100663, 2022). "In mice, swimming exercise results in increased levels of SIRT3 short form and physiological cardiac hypertrophy, characterized by increase in cardiomyocyte size without fibrosis or pathological remodeling." (PMID 35369299, 2022). "Moreover, SIRT3 deacetylates FOXO1, which translocates to the nucleus and increases autophagy as a protective mechanism to reduce cardiac hypertrophy." (PMID 34829803, 2021). "Others have shown that the SIRT3-dependent activation of anti-oxidative Foxo3a targets Ras activation and represses the activity of transcription factors such as GATA4 and NFAT involved in the development of cardiac hypertrophy." (PMID 32429302, 2020). "To investigate whether SIRT3 inhibits cardiac hypertrophy by inhibiting PARP-1 activity, we overexpressed SIRT3 in cardiomyocytes with Ad-SIRT3, then stimulate with ISO or PE for 24 h, and detect PARP-1 activity changes with anti-PAR antibody." (PMID 32139662, 2020). "In accordance with this, mice lacking SIRT3 show similar cardiac pathologies as the aged wild-type mice such as cardiac hypertrophy and fibrosis." (PMID 31652604, 2019). "It suggested that the different effects of NaHS on ISO-induced myocardial hypertrophy between WT mice and SIRT3 KO mice were not due to blood pressure or endogenous H2S level." (PMID 30647820, 2018). "In our present study, cardiac configuration, cardiac index, cardiomyocyte areas, and hypertrophic genes expression suggested that NaHS effectively attenuated myocardial hypertrophy in WT mice but not in SIRT3 KO mice." (PMID 30647820, 2018).